HOXA5 (homeobox A5)
Diseases named in the same sentence as HOXA5 in open-access papers (continued):
Sharing a sentence is not in itself a finding about the gene and the disease.
tumor (continued). "We also confirmed that HOXA5 affected tumor cells progression through regulating tumor cell proliferation." (PMID 34485110, 2021). "We subsequently investigated the inter-tumor heterogeneity of HOXA5 among different molecular subtypes based on the VERHAAK 2010 classification scheme." (PMID 34485110, 2021). "Some studies suggest that HOXA5 functions as an oncogene, whereas some suggest that it functions as a tumor suppressor 42-46." (PMID 34149926, 2021). "Some studies have also connected miR interference with HOXA5 downregulation, considered as a tumour suppressor gene in several cancer contexts." (PMID 33375038, 2020). "Ectopic expression of HOXA5 restrained cell proliferation, decreased cell viability, and inhibited tumor formation in vitro and in vivo." (PMID 32499530, 2020). "As transcription factors encoded by the homeobox genes have a pivotal role in governing the process of tumor angiogenesis, we decided to explore the function of HOXA5." (PMID 32373208, 2020). "HOXA5 is considered a regulator involved in embryonic development and cellular differentiation and a tumor suppressor." (PMID 32499530, 2020). "In xenograft animal models, we found that a decrease of HOXA5 effectively enhanced tumor growth and increased microvessel densities." (PMID 32373208, 2020). "Our findings highlight the importance of Sp1/miR-130b-3p/HOXA5 axis in tumor angiogenesis and recurrence, and implicate HOXA5 as a potential target for HCC treatment." (PMID 32373208, 2020). "It is worth noting that previous studies considered HOXA5 as a tumor-suppressor mainly due to its capacity to inhibit tumor proliferation and metastasis but not angiogenesis." (PMID 32373208, 2020). "As a tumor suppressor gene, HOXA5 inhibits NSCLC metastasis through regulating cytoskeletal remodeling." (PMID 31257678, 2019). "Elevated expression of HOXA5 strongly reduced tumor growth and prevents metastasis through forcing cancer stem cell differentiation." (PMID 31013831, 2019). "In order to study the effects of HOTAIR and HOXA5 on HL-60 cells in vivo, we established xenograft tumor model in nude mice." (PMID 31168296, 2019). "The volume of tumor in the M-oe-HOTAIR + oe-HOXA5 group was significantly lower than that in the M-oe-HOTAIR group (p < 0.05)." (PMID 31168296, 2019). "IPA analysis of differentially expressed genes indicated that HOXA5 short RNA activated canonical pathways of “Cell viability of tumor cell lines” and inhibited those of “Organismal death”, “Morbidity and mortality”, “Cell death”, and “Apoptosis”." (PMID 31159758, 2019). "Watson et al11 reported that increased DNA methylation in the HoxA5 promoter region contributed to tumour growth via down‐regulation of HoxA5 expression." (PMID 30039914, 2018). "In some instances, HOXA5 hypermethylation correlates with HOXA5 downregulation and tumor progression." (PMID 29615582, 2016). "To further explore the translational potential of HoxA5 in limiting tumor angiogenesis and/or neoplastic progression, we investigated the effects of a topically-applied HoxA5 transgene in K14-HPV16 mice." (PMID 25821967, 2015). "In order to confirm the observed nodules were derived from our injected tumor cells, immunohistochemical staining was performed by utilizing anti-human vimentin as well as anti-HOXA5 antibodies." (PMID 25875824, 2015). "We next evaluated the function of HOXA5 in cell migration directly, which is the most critical step of tumour invasion and metastasis." (PMID 25875824, 2015). "Using this genetic model, we examined the impact of sustained EC expression of HoxA5 on post-natal vascular development, pathological angiogenesis and de novo tumor progression." (PMID 25821967, 2015).
tumor (continued). "Tumor growth was quantitatively evaluated over a 32 day period revealing a marked reduction in tumor growth in mice expressing EC HoxA5." (PMID 25821967, 2015). "To examine the efficacy of targeting HoxA5 therapeutically to quell pathologic or tumor angiogenesis, we generated an inducible, transgenic mouse model of sustained HoxA5 expression in ECs." (PMID 25821967, 2015). "Low endogenous expression level of HOXA5 and the downregulation of HOXA5 by oncogenic miR-26a-2 suggested that HOXA5 has a tumor-suppressive role in LPS cells." (PMID 26219418, 2015). "By restoring expression of HoxA5 to angiogenic vasculature, either using a murine genetic model or via topical application of a HoxA5 transgene, both wound and tumor-induced angiogenesis and neoplastic progression were inhibited." (PMID 25821967, 2015). "A total of 147 genes were differentially methylated between tumor and matched tumor-adjacent gastric tissue, with HOXA5 and hedgehog signalling being the top-ranked gene and signalling pathway, respectively." (PMID 24674026, 2014). "Finally, we did not conduct mechanistic in vitro or in vivo studies to directly verify the functional role of HOXA5 in modulating tumor biology." (PMID 40805172, 2025). "In solid tumors, HOXA5 may facilitate tumor progression by enhancing vascularization, cellular plasticity, and stemness." (PMID 41209012, 2025). "This seemingly contradictory outcome may be explained by HOXA5’s broader tumor-suppressive functions." (PMID 40805172, 2025). "These collective findings suggest that HOXA5 plays a tumor-suppressive role across multiple cancer types and may serve as a valuable prognostic biomarker and potential therapeutic target." (PMID 40805172, 2025). "Although CD31 and fibronectin did not retain independent prognostic value in multivariable analysis, their downregulation in the high-HOXA5 group may reflect a biologically less aggressive tumor phenotype." (PMID 40805172, 2025). "Previous studies have identified HOXA5 as a tumor suppressor in various cancers." (PMID 39420439, 2024). "Despite this well-established function as a tumor suppressor, several studies indicate that HOXA5 may act as an oncogene in certain organs." (PMID 37626900, 2023). "Tumor purity was negatively associated with the expression of HOXA4 and HOXA5 in LUAD (P<0.05)." (PMID 35370463, 2022). "Importantly, RA treatment induced expression of potential tumor-suppressive genes, HOXA5 and ELF3, also in the CSC-like cells." (PMID 36497371, 2022). "Similarly, HOXA5 is underexpressed in both the CC tissues and cell lines, and its overexpression inhibits tumor progression by regulating AKT/p27 activation." (PMID 34617205, 2022). "Since the EMT pathway is an important regulator of tumor progression, we hypothesized that HOXA5 inhibited RCC metastasis by suppressing this pathway." (PMID 36536414, 2022). "We also identified HOXA5 as a novel tumor suppressor in RCC." (PMID 36536414, 2022). "HOXA5 overexpression significantly inhibited the proliferation and tumor growth." (PMID 36167790, 2022). "HOXA4 or HOXA5 may serve as tumor-suppressors in the occurrence and development of LUAD by acting on immune cells or affecting the proliferation, migration and invasion of LUAD cells." (PMID 35370463, 2022).
tumor (continued). "The gain-of-function of HOXA5 in CC cell lines confirmed that HOXA5 could act as a tumor suppressor by inducing the expression of cell cycle inhibitor p27 and suppressing the phosphorylation of AKT." (PMID 34617205, 2022). "In this work, the expression profile of the HOXA5 in multiple tumor types was mapped." (PMID 34485110, 2021). "Besides, tumor cells cycle was arrested at G2/M phase when inhibited HOXA5 expression implying its role in mediating cell cycle." (PMID 34485110, 2021). "It revealed that apart from promoter hypermethylation, a reduced mRNA expression of the homeobox A5 (HOXA5) gene (which functions as a tumor suppressor in the development of GC) was also observed in gastric cardiac IM, suggesting a possible role of this gene in the development of gastric IM." (PMID 34071181, 2021). "Critically, HOXA5 can arrest cell cycle at G2/M phase to inhibit tumor cell proliferation." (PMID 34485110, 2021). "Also, for HOXA5 it was demonstrated that increased DNA methylation in the HOXA5 promoter region correlates with decreased expression of the gene during tumor progression." (PMID 33547267, 2021). "Furthermore, we demonstrated that HOXA5 was down-regulated in HCC and its down-regulation was associated with larger tumor size, shorter overall survival, and higher recurrence probability." (PMID 32373208, 2020). "Here, we report the role of HOXA5 in tumor angiogenesis of HCC." (PMID 32373208, 2020). "HOXB9, HOXD10 and HOXA5 were expressed at low levels in GC and acted as tumour suppressors." (PMID 32907552, 2020). "Clinicopathological analyses revealed that HOXA5 was negatively correlated with tumor size and AFP." (PMID 32373208, 2020). "As a member of the HOX family, HOXA5 plays an important role in tumor development and progression." (PMID 32373208, 2020). "In this study, we demonstrated that HOXA5 was an HCC tumor suppressor." (PMID 32373208, 2020). "Moreover, in NSCLC, miR-196a antagonizes the inhibitory tumour growth effect of HOXA5, partially contributing to an increasingly invasive phenotype." (PMID 33375038, 2020). "Next, cell growth curves, MTT assays, and tumor xenografts showed that HOXA5 protein could inhibit tumor formation and progression by inhibiting cell proliferation." (PMID 32499530, 2020). "This study has not only experimentally validated the regulation of the expression of tumor-suppressive mRNAs such as HOXA5, MTSS1, PTEN, and RECK by MAGI2-AS3 in HGSC but also has suggested a network of how various pathways converge to aid in tumor suppression." (PMID 31842477, 2019). "Thus, the functional significance of HOXA5 in tumor development and progression is likely dependent on the type of cancer cells involved." (PMID 31159758, 2019). "Evidence from DMR and FL analyses indicated that dietary folate and alcohol intake may be associated with genomic regions with tumor suppressor activity such as the GSDMD and HOXA5 genes." (PMID 30940212, 2019). "Here, we confirmed that HOXA5 was significantly down‐regulated in paired NSCLC tumours." (PMID 28338293, 2017). "Altogether, these data raise the possibility that HOXA5 may become a potential novel therapeutic agent limiting tumor progression." (PMID 29615582, 2016). "To further explore the anti-angiogenic potential of HoxA5 during de novo tumor progression where early development of angiogenic vasculature accompanies neoplastic progression, we intercrossed HoxA5-tTA mice with a mouse model of de novo squamous carcinogenesis, e.g., K14-HPV16 mice." (PMID 25821967, 2015).
tumor (continued). "Together, these results demonstrate that HoxA5 is a novel and potent regulator of tissue angiogenesis, that may also have therapeutic efficacy in limiting tumor angiogenesis thereby impairing de novo tumor progression." (PMID 25821967, 2015). "The enrichment of HOXA5- and Aplidin-induced genes in the methionine-deprived samples may be consistent with the anti-tumor potential of methionine deprivation." (PMID 25849282, 2015). "Together these findings indicate that HoxA5 may have tremendous therapeutic potential in limiting tumor angiogenesis and stabilizing hyper-permeable tumor vasculature." (PMID 25821967, 2015). "In addition, we evaluated the therapeutic potential of topically-applied HoxA5 to limit tumor angiogenesis." (PMID 25821967, 2015). "Considering the oncogenic role of miR-26a-2 in human LPS cells, we hypothesized a tumor suppressive role of HOXA5 in DDLPS cells." (PMID 26219418, 2015). "Taken together, the data from these studies indicated that HOXA5 may serve as a tumour suppressor gene in breast cells." (PMID 25875824, 2015). "The higher level of methylation in tumors compared to tumor-adjacent gastric tissues that was observed in GoldenGate analysis was observed again for both HOXA5 (mean difference = 16.4%, P < 0.001 by paired t-test) and WNT5A (20.0%, P < 0.001) in this independent series." (PMID 24674026, 2014). "In addition, loss of HOXA5 and HOXA9 expression is generally associated with an increased resistance to apoptosis and tumour survival, although both of these genes are expressed at relatively high levels in SK-OV3 compared to normal ovarian tissue and OV-90." (PMID 20219106, 2010). "Our study posits that the HOXA5 gene may function as a tumor suppressor in NSCLC." (PMID 39121297, 2024). "Accordingly, HOXA5 may regulate MXD1 expression in a tumor origination-dependent manner." (PMID 36167790, 2022). "Therefore, we speculated that HOXA5 may also function as a tumor suppressor in ACC via targeting AKR1B10 and enhancing its expression level." (PMID 34027794, 2021). "Consequently, these studies showed that the overexpression of HOXA5 could prevent tumor progression and transition cancerous cells to a normal-like state 47-49." (PMID 34149926, 2021). "However, the ectopic expression of HOXA5 had little impact on tumor angiogenesis." (PMID 32373208, 2020). "Thus, HoxA5 could be repressed during development and then selectively activated in adult EC when endogenous levels are reduced during tumor-induced angiogenesis." (PMID 25821967, 2015). "Through multi-omics integration and functional validation, this study unveils its pivotal role in the spatial tumor immune microenvironment and establishes its therapeutic target value in AML, laying the groundwork for HOXA5-based precision therapies." (PMID 41209012, 2025). "Of those, eight (HOXA3, HOXA5, ATP10A, SOX2, MIR922, ADAMTSL1, KHDRBS2, and LITD1) were hypermethylated in at least one LS tumor group like here in FAP normal, whereas NEDD4L, and FOXP1 were hypermethylated in LS carcinomas and here in LS normal." (PMID 40753397, 2025). "HOXA5, WT1, and LHX2 are fibroblast specific motifs that are drivers of tumor microenvironment remodeling, and their potential targets were highly correlated with collagen - containing extracellular matrix in KEGG analysis." (PMID 38702814, 2024). "In our study, we analyzed HOXA5 expression according to molecular classification, the POLE gene functions in DNA duplication, and tumor suppression." (PMID 37834206, 2023). "It is well known that some transcription factors are responsible for the transcription activity of uPA in various tumor cells, such as Sp1, AP1 and HOXA5." (PMID 36612038, 2022). "Intriguingly, HOXA5 overexpression significantly up-regulated the expression of MXD1, a tumor suppressor that can antagonize the formation of MYC-MAX complex, in ECCA cells." (PMID 36167790, 2022).
tumor (continued). "MiR-130b-3p has been determined to target multiple tumor suppressors, such as PTEN, HOXA5, and SASH1, in various types of cancer, resulting in cancer progression and treatment resistance." (PMID 36217202, 2022). "Our results demonstrated that HOXA5 was down-regulated in HCC tissues and its expression closely correlated with tumor size." (PMID 32373208, 2020). "Our results demonstrated that HOXA5 was down-regulated in HCC tissues and its expression was closely correlated with tumor size." (PMID 32373208, 2020). "In some regions identified by DMRs or FL analysis, mapped genes are known to act as tumor suppressors such as the GSDMD and HOXA5 genes." (PMID 30940212, 2019). "A last, in vivo assay was performed to assess the tumor formation in nude mice in order to explore the roles of HOTAIR and HOXA5 in cell apoptosis and proliferation." (PMID 31168296, 2019). "Homeobox A5 (HOXA5), a member of the HOX family, plays an important role in tumor development and morphogenesis, although opposite effects on tumorigenesis have been observed, depending on the tissue type." (PMID 31159758, 2019). "The relative level of hematopoiesis gene (e.g., Hoxa5, Hoxa7, Evi1, and Meis124,25) mRNA expression was decreased in CXCR2−/− tumor-bearing mice." (PMID 31395859, 2019). "The mRNAs HOXA5, MTSS1, PTEN, and RECK are reported to have important tumor-suppressive roles in OC, though their role in HGSC is not specifically shown." (PMID 31842477, 2019). "The percentage of methylation in the HOXA5, HOXA2, and HOXA6 genes in CRC were up to 67.62, 58.36, and 31.32%, respectively, and ranked first in CRC among all human tumor tissues." (PMID 31165042, 2019). "Our findings highlight the anti-tumor ability of HOTAIR silencing in AML, suggesting that silencing HOTAIR was able to inhibit AML progression through HOXA5 promoter demethylation by decreasing Dnmt3b." (PMID 31168296, 2019). "Suppressing HOTAIR upregulates the HOXA5 level and downregulates MMP2 and MMP9, which are critical players in tumor invasion and metastasis." (PMID 28931862, 2017). "For instance, in LSCC we observed four TFs (HOXA4, HOXA5, TAL1, ZNF132) undergoing promoter hypermethylation in at least 50 % of the LSCC tumour samples where these TFs were underexpressed." (PMID 27562343, 2016). "A total of 219 CpG sites (185 hypermethylated and 34 hypomethylated) in 147 unique genes were significantly differentially methylated between tumor and tumor-adjacent gastric tissue (FDR = 0.001), with the top three CpG sites located in HOXA5, SFRP1 and CCNA1." (PMID 24674026, 2014). "HOXA5, HOXD10 and HOXD11 showed the highest expression levels and their up-regulation was then validated by qRT-PCR in tumor samples as well as in cell lines." (PMID 22227861, 2012). "In vivo HOXA5 silencing reduced GSC tumor-derived growth, and mice bearing HOXA5-silenced GSC lines had prolonged overall survival rates, indicating the importance of HOXA5 in GSC proliferation and tumor development." (PMID 39858044, 2025). "Through multi-omics integration and functional verification, this study revealed for the first time its pivotal role in the tumor space immune microenvironment and its therapeutic target value in AML, laying the foundation for the development of precision treatment based on HOXA5 molecular typing." (PMID 41209012, 2025). "Upregulation of HOXA5 in non-stem tumor cells (NSTCs) resulted in increased tumorsphere formation and size, confirming the role of HOXA5 in GSCs." (PMID 39858044, 2025). "Moreover, the expression levels of CD31 and CD34 in tumor specimens from 314 HCC patients were also detected by IHC staining, to investigate the correlation between HOXA5 and MVD." (PMID 32373208, 2020). "Delivery of miR-181d-5p via CAF sEVs promoted cell proliferation, invasion, migration, EMT, and inhibited cell apoptosis, through repression of CDX2 and HOXA5; in vivo study showed CAF mediated delivery of miR-181d-5p mimic increased tumor growth rate, volume, and weight." (PMID 32957712, 2020).